NOTCH3 (notch receptor 3)
Diseases named in the same sentence as NOTCH3 in open-access papers (continued):
Sharing a sentence is not in itself a finding about the gene and the disease.
tumor (continued). "However, NOTCH-1 and NOTCH-3 were positively correlated with the tumor grade and stage." (PMID 36476410, 2022). "In addition, MMP-14 and MMP-28 were found to promote tumor metastasis by inducing Notch3 signaling." (PMID 34195229, 2021). "Similarly, CD4+ naive T cells (cluster 0) located at the core of the tumor have significantly higher activation levels in angiogenesis, epoxygenase cytochrome P450, NOTCH3 signaling, lipid particle organization and other pathways than those at the edge of the tumor." (PMID 34513820, 2021). "In a word, FAM225A/miR‐613/NOTCH3 axis may play a tumor‐facilitator in CRC cell progression." (PMID 32343052, 2020). "Notably, in vivo administration of Juglone to human T-ALL xenotransplant models significantly reduced tumor growth, finally fostering the exploitation of Juglone-dependent Notch3 inhibition to perturb the ER stress/UPR signaling in Notch3-dependent T-ALL subsets." (PMID 33071287, 2020). "Therefore, we investigated whether genetic HDAC6 inactivation would impair tumor growth by HDAC6 silencing in the Notch3-dependent cell line TALL1." (PMID 29643474, 2018). "Speculatively, treatment with HDAC6i might exert stronger therapeutic effects in tumor cells bearing Notch3 mutations in the absence of Notch1 mutations, such as the TALL1 cell line." (PMID 29643474, 2018). "Therefore, Notch3 upregulation in urothelial cancer cells could be a critical determinant of overall tumor growth." (PMID 28416766, 2017). "The absence of stromal Notch3 was associated with an increase of tumour growth." (PMID 28719575, 2017). "Furthermore, the function we describe here in tumour angiogenesis could account for some paradoxical observations regarding Notch3." (PMID 28719575, 2017). "In addition, Notch3 knockdown decreased tumor weight compared to control values." (PMID 28416766, 2017). "Finally, CD133hi tumour cells (enriched in areas with stromal infiltrates) also expressed Notch3 protein and, using gene set enrichment analysis, CD133hi cells compared with CD133lo cells had elevated mRNA levels of transcripts downstream of Notch signalling (GSE69280)." (PMID 26858125, 2016). "Therefore, MUC4/Y-AMOP domain-promoted tumour angiogenesis and metastasis may be partly due to the activation of NOTCH3." (PMID 27287498, 2016). "Therefore, we hypothesized that endothelial Jagged1 could also be acting as an angiocrine factor activating Notch3 in adjacent tumor cells, and consequently regulating proliferation and de-differentiation." (PMID 26213336, 2015). "Therefore, we supposed that Notch3 might inhibit β-catenin and result in maintaining the stemness of the tumor cell." (PMID 25668819, 2015). "However, overall, it is apparent that hypoxic gliomaspheres mimic the in-vivo tumor condition better than the other tissue culture model as the upregulation of Notch genes (Notch1, Notch2, Notch3, Dll1, Hes1, Hey1 and Hey2) is further enhanced upon exposure to hypoxia." (PMID 25734817, 2015). "Moreover, Notch3 depletion reduces PAX3-FOXO1 alveolar RMS tumor growth in vivo." (PMID 24797362, 2014). "Thus, Jagged1 is an important ligand of Notch3 and is involved in the pathogenesis of neoplasms." (PMID 23426998, 2013). "On the other side, several mutational landscape of the NOTCH gene family (particularly NOTCH1 and NOTCH3), observed in a subset of SCLC, supports a context-dependent tumor-suppressive role." (PMID 40563292, 2025). "By contrast, module 2 and 3, which were only downregulated in EGF-stimulated SHP2WT cells, contained several tumor suppressors, such as NRG1, MAP3K1, CAVIN3, EPHA3/7, CTNNA1/3, and NOTCH3." (PMID 40631144, 2025). "In contrast to the tumour suppressor NOTCH1, NOTCH2 and NOTCH3 have demonstrated an oncogenic role in BCa and correlation with poor prognosis." (PMID 41008920, 2025).
tumor (continued). "In contrast, co‐transfection with Lv‐oe‐LINC00958 and miR‐129‐2‐3p agomir led to increased miR‐129‐2‐3p expression, decreased NOTCH3 levels (p < 0.05), and a reversal of LINC00958‐induced tumor growth (p < 0.05)." (PMID 41090505, 2025). "To further characterize tumor cells with NOTCH activity, we produced organoids from sorted NOTCH3+/high and NOTCH3−/low CRC cells." (PMID 41034989, 2025). "In line with this notion, we detected NOTCH3+/HTR2B + cells within the EpCAM + epithelial and tumor cell population in CRC tissues." (PMID 41034989, 2025). "In summary, these data provide evidence that HTR2B+/high and NOTCH3+/high CRC cells are overlapping populations with shared common features, and both represent tumor cells with elevated EMT." (PMID 41034989, 2025). "The result demonstrated a significant increase in HSPA6 and NOTCH3 expression, but a significant decreased in GPD1L, PKP2 and SMAD9 in CRC tumor group when compared to those in normal group (all P < 0.001)." (PMID 40796704, 2025). "The results showed that, compared to normal samples, HSPA6 and NOTCH3 were dramatically increased, while GPD1L, PKP2, and SMAD9 were dramatically decreased in tumor samples in both the CRC training dataset and the CRC validation dataset (all P < 0.05)." (PMID 40796704, 2025). "KLF4 upregulation combined with Notch3, HER3, and p-Smad2 downregulation disintegrated the regulatory network of tumor stemness from multiple dimensions." (PMID 40438682, 2025). "In the CRC tumor group, the expression levels of HSPA6 and NOTCH3 protein were dramatically up-regulated, while GPD1L, PKP2, and SMAD9 protein were dramatically down-regulated (all P < 0.05)." (PMID 40796704, 2025). "Meanwhile, when compared with normal group, the HSPA6, NOTCH3 and PKP2 expression were significantly increased in LUAD tumor group, but GPD1L and SMAD9 expression were dramatically decreased in control group (all P < 0.001)." (PMID 40796704, 2025). "We also provide evidence that not only HTR2B, but also NOTCH3 are regulated by mTORC1, HTR2B+/high and NOTCH3+/high CRC cells display overlapping populations with shared common features, and both represent tumor cells with elevated EMT levels." (PMID 41034989, 2025). "Ultimately, their findings supported a tumour-suppressive function for NOTCH1, and they proposed a similar suppressive role for NOTCH2 and NOTCH3." (PMID 41008920, 2025). "Other notable NET-related CSM and SP genes include previously discussed IGF-2 and IGFBP3 genes and genes related to the stromal component of the tumor (COL5A3, FN1, and NOTCH3)." (PMID 40522948, 2025). "The IHC results demonstrated that CAF signature genes COL1A2, MFSD5, NOTCH3, and PRSS3 were highly expressed in tumor tissues." (PMID 40781483, 2025). "NOTCH1 has been revealed as a tumour suppressor; in contrast, NOTCH2 and NOTCH3 have demonstrated an oncogenic role in BCa." (PMID 41008920, 2025). "In contrast, the FPR3/NFATc1/NOTCH3 axis exerts tumor-suppressive effects in diffuse-type GC by modulating calcium flux: FPR3 activation restricts NFATc1 nuclear translocation, downregulating NOTCH3-AKT/mTOR signaling and suppressing stemness." (PMID 40977684, 2025). "NOTCH3 was found to be overexpressed in COAD, promoting tumor growth as verified through various assays." (PMID 39286249, 2024). "Knockdown of AAK1 substantially suppressed tumor growth, tumor weight, as well as the expression of AKK1, Notch3, GLS, MMP-2, MMP-9, and Ki-67 percentage." (PMID 38169546, 2024). "Meanwhile, NOTCH3 expression in normal human dermal fibroblasts can be stimulated by direct co-culture with OSCC cell lines, which serve as a pro-tumour loop." (PMID 38926351, 2024). "Functional experiments demonstrated that NOTCH3 knockdown inhibited BLCA cell proliferation, migration, invasion and significantly suppressed tumor growth and metastasis in vivo as well." (PMID 39557868, 2024).
tumor (continued). "In cancer cells, apelin signaling has been shown to promote tumor growth through mechanisms involving the PI3K/Akt pathway, as well as the activation of Notch3 and STAT3." (PMID 39684225, 2024). "Tumor promoting CAFs displayed high expression of CCDC80, SFRP2, VCAN, COL8A1, RGS5, HIIGD1B, NOTCH3, and NDUFA4L2." (PMID 38525245, 2024). "Exploring Notch-specific targets such as NOTCH3-targeted antibody drug conjugates and/or NOTCH4 monoclonal antibodies can help determine if there is greater tumor response and less toxicity with more specific targeted therapy in uLMS." (PMID 38927890, 2024). "NOTCH receptor 3 (NOTCH3) is known to regulate the transcription of oncogenes or tumor suppressor genes, thereby playing a crucial role in tumor development, invasion, maintenance, and chemotherapy resistance." (PMID 38906903, 2024). "Although our research offers significant insights into NOTCH3’s involvement in COAD, real-world application demands acknowledgment of patient diversity and the intricacies of tumor biology." (PMID 39286249, 2024). "RAMP2-AS1 functions by interacting with DHC10/NOTCH3/HES1 signaling cascade and reduces GBM tumor progression by inhibiting NOTCH3." (PMID 38059120, 2024). "Particularly, NOTCH3 is profoundly overexpressed in COAD and correlates strongly with tumor proliferation, invasion, and migration, suggesting its potential as a biomarker and therapeutic target." (PMID 39286249, 2024). "Another matrix CAF subcluster, C11, was linked to angiogenesis and highly expressed NOTCH3 (an important receptor in vascularization and angiogenesis), COL18A1 (involved in angiogenesis regulation), COL4A1, and COL4A2, which might promote the proliferation and metastasis of tumor." (PMID 38010945, 2024). "RNA levels of potential target genes IGF1R, NOTCH3 and OLFML2A were increased in 3D tumor spheroid culture compared to cells grown in 2-D culture to normal, ∼70% confluence." (PMID 38109320, 2024). "We used metformin, DAPT, and evodiamine in the murine tumor model to demonstrate that KLF10, the Notch signaling pathway and Notch-3 are potential therapeutic targets in PDAC with KLF10 deficiency." (PMID 37308977, 2023). "In summary, we observed an inverse relationship between NOTCH1 and NOTCH3 levels and cisplatin responsiveness, overall protective effects by CAFs, and a potential link between JAG2 expression with tumor cell survival." (PMID 38001580, 2023). "Mechanically, interference with Notch3 significantly reduced the proportion of macrophage in tumor tissue while no obvious changes were detected in peripheral blood of mice, suggesting Notch3 might participate in the regulation of macrophage recruitment and thus promote tumor growth of CRC." (PMID 36647017, 2023). "For both UT-SCC-24B and UT-SCC-42B cells, an increase in the expression of N1ICD, the full length of NOTCH3 protein, and N3ICD was observed in CAFs/HNSCC cocultures compared to tumor monocultures, confirming the qPCR results." (PMID 38001580, 2023). "Notch3 was closely related to immune infiltration (macrophages, CD4+ T cells, and dendritic cells) and tumor proliferation." (PMID 37284062, 2023). "Increased Notch3 expression in human CRC tissues and CRC cell lines has also been reported, and is involved in tumor progression and aggressiveness of CRC." (PMID 36647017, 2023). "Others have identified Notch3 as responsible for maintenance of CD24+, ITGB4+ tumor-propagating cells in a Kras model highlighting the possibility that Notch activation is required for this phenotype across models." (PMID 37882674, 2023). "Our analyses of tumor samples collected from patients with CRC revealed a positive correlation between LIN28B, CLDN1, and NOTCH3 expression and CRC metastasis to the liver." (PMID 37318881, 2023).
tumor (continued). "The expression of NOTCH1 and NOTCH3 mRNA and fold changes in monocultures of UT-SCC-42B, UT-SCC-24B, and CAFs, compared to 3D cocultures of different tumor cells with varying ratios to CAFs (3:1, 1:1, 1:3), was performed by qRT-PCR." (PMID 38001580, 2023). "IGF2BP3 and N3ICD levels were potently upregulated in NPC primary tumor samples from the patients with metastatic NPC compared to those without metastasis, suggesting the significant relevance of the IGF2BP3/Notch3 axis in NPC." (PMID 37853162, 2023). "Taken together, these observations suggest that while Notch1 clearly can act as a tumor suppressor in HNSCC, Notch3 has an oncogenic role, is involved in a distinct signaling cascade and contributes to the survival of metastatic derivatives of tumor cells." (PMID 37202533, 2023). "Therapy resistance pathways are potentially regulated by JAG1/Notch3-mediated crosstalk between CAFs and BC cells, through the expansion of CD44+CD24 low tumor-initiating and therapy-resistant cells." (PMID 35682974, 2022). "From this study, proteins of interest identified by tandem MS-MS that were decreased in sera from tumor-bearing rats treated with OKN-007, compared to untreated, included ABCA2, ATP5B, CNTN2, ITGA3, KMT2D, MYCBP2, NOTCH3, and VCAN." (PMID 35053843, 2022). "NOTCH3 is an important member of the NOTCH family, which is involved in the development and progression of various cancers by regulating the tumour microenvironment, promoting tumour formation, angiogenesis, migration, and invasion processes." (PMID 35136410, 2022). "Proteins of interest identified by tandem MS-MS that were decreased in sera from tumor-bearing rats that were either OKN-007-treated or untreated included ABCA2, ATP5B, CNTN2, ITGA3, KMT2D, MYCBP2, NOTCH3, and VCAN." (PMID 35053843, 2022). "For example, overexpressed Notch-1 promotes epithelial-mesenchymal transition (EMT), and consequently, invasion and migration of tumor cells in ovarian, breast, and lung cancers, while in NSCLC, downregulated Notch-3 plays a tumor-suppressive role." (PMID 36143328, 2022). "Western blotting further proved that the expression of Notch3, as well as β-catenin downstream genes CBP (Lys1535)/p300 (Lys1499) and p-EGFR (Tyr1068) in the tumor tissues, was reduced." (PMID 35463301, 2022). "The expression levels of oncogenes or tumor-related genes, such as BRAF, NOTCH3, and TERT, were higher in tumor tissues compared with paired normal tissues." (PMID 36092890, 2022). "In vivo experiments confirmed that decreased lncRNA00673 significantly inhibited tumor formation ability of HCC cells through Notch1 and Notch3 down-regulation." (PMID 33804511, 2021). "Notch3 silencing in TKI-resistant TNBC cells induces EGFR dephosphorylation and promotes its intracellular arrest, which increases tumor cell sensitivity to TKI–gefitinib treatment." (PMID 34195229, 2021). "Immunohistochemistry for Notch3 expression in 105 TNBC tissues showed that its expression is positively correlated with tumor microvascular density (MVD), which suggests a potential pro-angiogenic role of Notch3." (PMID 34195229, 2021). "In HCC and pancreatic ductal adenocarcinoma (PDAC), Notch3 signaling activates the COX-2 and ERK1/2 pathways, which subsequently enhance the migration and invasion of tumor cells by upregulating the expression of MMP-2 and MMP-9." (PMID 34195229, 2021). "The primary treatment-naïve tumor was extracted in the diagnosis and had MCL1 and NOTCH3 amplifications, and a BRCA1 deletion." (PMID 34680239, 2021). "It has been shown that inhibitors blocking the histone-modulating functions of KMT2A, and related genes potently inhibit tumour cell proliferation in glioma cells, a partly by DNA methylation of NOTCH1 and NOTCH3 genomic locus." (PMID 34944837, 2021).
tumor (continued). "In high grade serous OC, a link between Notch3 and ALDH1 has been reported, already recognized as important in tumor formation and drug resistance." (PMID 35582386, 2021). "To explore the effect of Notch3 on tumorigenesis, we examined the effects of modulating the Notch3-PTEN axis on the growth of MDA-MB-231-luc-N3ICD tumor cells in nude mice." (PMID 34006834, 2021). "MUC4, a large membrane-anchored glycoprotein, can facilitate tumor angiogenesis and increase tumor MVD in PC by activating Notch3 signaling and downstream pro-angiogenic genes, including VEGF-A and ANG-2." (PMID 34195229, 2021). "Mechanistically, miR-136 is able to suppress Notch3 expression by directly binding to its 3-UTR, thus acting as a tumor suppressor." (PMID 35582386, 2021). "While EMT was induced following 5‐FU exposure and subsequent NOTCH3 suppression in ESCC cells, continuous expression of ectopic ICN3 suppressed EMT and increased the sensitivity of tumor cells to 5‐FU." (PMID 34042293, 2021). "The NOTCH3 enhancer generated by NRF2 in cooperation with CEBPB establishes the NRF2-NOTCH3 axis and drives malignancy of NRF2-activated NSCLCs by promoting tumor-initiating activity." (PMID 33219226, 2020). "Immunohistochemistry (IHC) staining showed that tumor sections from ZIP4+ cell-injected mice expressed high levels of ZIP4, ALDH1, and NOTCH3, and Ki67." (PMID 33316986, 2020). "The significant positive correlation observed between Notch3 and IRE1α mRNA expression levels in human T-ALL primary tumor samples confirms the possible relevance of our observations for human T-ALL development." (PMID 33071287, 2020). "The most prevalent tumor suppressors identified were ADAM10, AJUBA, receptor interacting serine/threonine kinase 4 (RIPK4), NOTCH2, and NOTCH3, which were all shown to converge on the NOTCH pathway." (PMID 33322834, 2020). "Therefore, FAM225A/miR‐613/NOTCH3 axis may play a tumor‐facilitating role in CRC cell progression." (PMID 32343052, 2020). "This tumor can be subdivided into a common conventional-type ACC and a solid-type ACC: NOTCH1 (47% vs 7%), NOTCH2 (13% vs 0%), and NOTCH3 (7% vs 0%) were clearly more frequent in solid-type ACC than in conventional-type ACC." (PMID 32210163, 2020). "On the other hand, Notch3 was downregulated in OSCC cell lines, and its methylation status was significantly higher in tumor compared to normal tissues." (PMID 32796631, 2020). "In particular, it was demonstrated that stromal cells expressing Jagged1 on their surface were able to activate Notch3 on TNBC cells, thus promoting the expansion of cells resistant to chemotherapy and reinitiating tumor growth." (PMID 31379945, 2019). "Of note, NF-κB transcription factor mediates the enhanced generation of Treg in a Notch3-dependent T-ALL mouse model, thus suggesting a Notch3/CXCR4 synergism that facilitates tumor development by suppressing antitumor immune response." (PMID 31346528, 2019). "The studies by McAuliffe and colleagues strongly supported the specific role of Notch3 signaling pathway in CSC maintenance and tumor resistance to platinum both in vitro and in vivo." (PMID 30723507, 2019). "Loss of heterozygosity (LOH) with very high allelic frequency was observed in NOTCH3, TGFB1, EZH2 and KMT2C in the patient tumor, the subcutaneous PDX and the PDOX." (PMID 31732509, 2019). "This patient’s tumor cells also carried an amplification in each CTC of the 11q13.3 locus containing Cyclin D1 gene (CCND1), as well as gains of NOTCH3 (19p13.2), HTERT (5p15.33), and PDPK1 (16p13.3)." (PMID 31481116, 2019). "Knockdown of Notch3 in ESCC cells promotes EMT with the up-regulation of ZEB and impairs squamous differentiation mechanisms, leading to invasive growth and tumor cell dissemination." (PMID 27902974, 2017). "In conclusion, our results demonstrate that in U-87 MG cells, KMT2A positively regulates NOTCH1 and NOTCH3, and this KMT2A–NOTCH1/3 cascade is essential for the inhibition of tumor cell proliferation." (PMID 28968975, 2017).